FOXP3 (forkhead box P3)
Diseases named in the same sentence as FOXP3 in open-access papers (continued):
Sharing a sentence is not in itself a finding about the gene and the disease.
gastric cancer (continued). "Previous researches have supported the positive correlation between the transcription and expression of FOXP3 and the lesion grade of gastric cancer." (PMID 35037550, 2022). "FOXP3 has proven to participate in the aggressive activities of gastric cancer cells such as proliferation, migration and invasion via the TGF-β signaling pathway." (PMID 35037550, 2022). "PSMD7 is involved in the proliferation and apoptosis of gastric cancer cells and can be transcriptionally regulated by FOXP3." (PMID 35037550, 2022). "Of note, the upregulation of CD4+ TILs is accompanied by FOXP3+ Treg infiltrations in HER2-amplified gastric cancer." (PMID 36591290, 2022). "HGC-27 cells were also transfected with Ov-FOXP3 to perform gain-of-function experiments on the role of FOXP3 in gastric cancer." (PMID 35037550, 2022). "For other cancers, high levels of Foxp3-positive lymphocytes signal better prognoses, e.g., breast, prostate and gastric cancers." (PMID 35326661, 2022). "In our study, high ImmunoCRIT showed worse prognosis compared to low ImmunoCRIT, supporting the unfavorable prognostic role of peripheral Foxp3+ Tregs in gastric cancer." (PMID 34086741, 2021). "In gastric cancer, SUVmax showed a marginal association with CD3(+) lymphocytes and a significant association with FoxP3(+) Treg cells." (PMID 34103577, 2021). "To validate these findings, we carried out immunohistochemistry (IHC) to detect CD163 and FoxP3 proteins in our gastric cancer specimens." (PMID 34760687, 2021). "The results of our study showed that the oncogenic ability of cell proliferation and cancer promotion, represented by SKP2 expression in gastric cancer tissues, was repressed by the expression of Beclin-1 and FOXP3 and thus responded to the survival outcome." (PMID 34414959, 2021). "A rapid expansion of forkhead box P3+ (Foxp3+) Treg cells has been observed in the tumors of HPD patients with advanced gastric cancer treated with nivolumab." (PMID 33467713, 2021). "In our analysis, the levels of CD4+ T cell and FOXP3+ Treg infiltration were significantly higher in patients with T3 gastric cancer than patients with T1 and T2 gastric cancer." (PMID 34421887, 2021). "A retrospective study involving 598 gastric cancer patients suggested that high infiltration of FOXP3+ Treg was of better prognosis in patients on stages I-II, whereas the converse outcome was demonstrated in that of stages III-IV." (PMID 32685487, 2020). "In our previous study, we also found that Helios expressed both in Foxp3+ and Foxp3− lymphocytes infiltrated in gastric cancer." (PMID 32927747, 2020). "CD8+ T cells and FOXP3+ Treg cells are reported to be closely related and play important roles in tumor development and immune escape in breast, ovarian, and gastric cancers." (PMID 32983971, 2020). "Strong cytoplasmic staining of FoxP3 has been detected in gastric cancer cells, and low FoxP3 protein expression in these tumor cells predicts a good prognosis." (PMID 32206186, 2020). "Activation of Foxp3+ Tregs and noncoding miR-155, which are associated with activation of the signal transduction factor Stat3, may serve as prognostic factors in patients with chronic inflammation that predisposes them to development and progression of gastric cancer and metastasis." (PMID 32206186, 2020). "High FoxP3 expression in tumor cells predicts worse survival in gastric cancer, possibility related to interactions between tumor cells and lymphocytes in the microenvironment." (PMID 32206186, 2020). "We analyzed CD8+ and Foxp3+ TILs in combination with HEVs to determine their prognostic role in advanced gastric cancer (AGC)." (PMID 32823631, 2020).
gastric cancer (continued). "EBV-positive gastric carcinomas had higher incidences of tumoral PD-L1(+) and immune cell PD-L1(+), and larger numbers of CD8+, FOXP3+, and PD-1+ TILs than conventional gastric carcinomas (P < 0.05 for all comparisons)." (PMID 32498695, 2020). "Currently, the prognostic role of FOXP3+ TILs in gastric carcinomas remains unanswered; a high population of FOXP3+ TILs has been associated with both a better and worse prognosis, or not a reliable marker." (PMID 32498695, 2020). "Gastric cancer at the T3‐T4 stage exhibited higher levels of tumor‐infiltrating Foxp3 + Tregs (P = .007);." (PMID 31631566, 2019). "A total of 598 surgically resected FFPE primary gastric cancer samples in TMA were assessed for FOXP3, CD163, PD-L1, CD3, and CD8 markers, including 418 males and 180 females." (PMID 31174544, 2019). "In this study, a total of 598 surgically resected FFPE primary gastric cancer samples were assessed for FOXP3, CD163, CD3, CD8, and PD-L1 markers." (PMID 31174544, 2019). "More studies are needed to investigate the relationship between the T immunity cell and gastric cancer, especially forcing on Foxp3+ Tregs and the influence of location and mutual relations between cells." (PMID 29682534, 2018). "Correlation between upregulated FOXP3 expression, cancer stage, shorten progression-free survival, and poor prognosis was observed in breast, ovarian, and stomach cancers." (PMID 29785404, 2018). "The correlation coefficient between the expression of CD8 and Foxp3 in gastric cancer tissues was 0.479 (p < 0.01)." (PMID 29025424, 2017). "After optimization of the antibody dilution and antigen recovery conditions, CD8+T, Foxp3 and PD-L1 were detected in gastric cancer tissues." (PMID 29025424, 2017). "A total of 14 articles, including 1,486 patients with gastric cancer, researched the clinical outcome of patients with high density of FOXP3+ TILs." (PMID 28915679, 2017). "In the entire cohort, there was a strong to very strong correlation between CD3+, CD8+ and FoxP3+ cells, with similar findings in esophageal and gastric cancer, respectively." (PMID 29069772, 2017). "We have recently reported that FOXP3 inhibited proliferation of gastric cancer (GC) cells through activating the apoptotic signaling pathway." (PMID 29089565, 2017). "According to our study, the accumulation of CD8+, CD3+, CD57+ TILs and depletion of FOXP3+ TILs were all favorable prognostic factors in gastric cancer." (PMID 28915679, 2017). "We showed previously that in gastric cancer short CD8+-FoxP3+ distances both in the epithelial and stromal compartment are associated with a favourable metastasis-free survival and OS." (PMID 27494875, 2016). "For example, in gastric cancer, FOXP3 acts as a tumor suppressor protein by inhibiting the activity of NF-κB and by interfering with the expression of COX2." (PMID 26305693, 2015). "Increased CD19+CD24hiCD38hiBregs positively correlate with levels of CD4+FoxP3+Tregs in gastric cancer." (PMID 26378021, 2015). "As expected, we found a positive correlation between CD24hiCD38hiBregs and CD4+FoxP3+Tregs in gastric cancer." (PMID 26378021, 2015). "For GC, the prognostic significance of tumor-infiltrating FoxP3+ T cells for the survival of patients with gastric cancer remains controversial." (PMID 24827118, 2014). "Our study confirmed the importance of CCR7 expression in gastric cancer cells and intratumoral FOXP3+ Tregs as prognostic factors, which were correlated with overall survival and lymph node metastasis in gastric cancer, in line with the previous findings." (PMID 24040244, 2013). "CCR7+ tumor cells and FOXP3+ Tregs were assessed by immunohistochemistry in tissue microarrays containing gastric cancer from 133 patients." (PMID 24040244, 2013). "The result showed that there was a significantly positive correlation between CCR7 positive score of gastric cancer cells and intratumoral FOXP3+ Treg cell number (r = 0.949, P<0.001)." (PMID 24040244, 2013).
gastric cancer (continued). "In our series, similarly, using Kaplan-Meier analysis, the results showed that the prevalence of high intratumoral FOXP3+ Tregs was significantly related to poor survival rates of patients with gastric cancer." (PMID 24040244, 2013). "The expression levels of CCR7 and FOXP3 in tissue microarrays of gastric cancer were examined by immunohistochemical analysis." (PMID 24040244, 2013). "The aim of this study was to investigate the prognostic value of chemokine receptor CCR7 expression and intratumoral FOXP3+ regulatory T cells (Tregs) in gastric cancer." (PMID 24040244, 2013). "In this study, we investigated the prognostic value of CCR7 expression in gastric cancer cells and intratumoral FOXP3+ Tregs, and the relationship between them in gastric cancer." (PMID 24040244, 2013). "In the present study, it was interesting that either CCR7 expression or intratumoral FOXP3+ Tregs was found to be an independent prognostic factor in gastric cancer." (PMID 24040244, 2013). "This is, to the best of our knowledge, the first report demonstrating that high CCR7 expression in gastric cancer cells was in parallel with marked infiltration of intratumoral FOXP3+ Tregs in the tumor microenvironment." (PMID 24040244, 2013). "That is, the migration factors for Foxp3+ T regs were mainly produced in the peri-tumoral region as a result of the tumour–stromal reaction at the early stage of gastric cancer." (PMID 18087278, 2008). "In the current study, we analysed the prevalence of Foxp3+ cells in gastric cancer by immunohistochemistry." (PMID 18087278, 2008). "In the present study, we investigated the prevalence and localisation pattern of Foxp3+ cells in gastric cancer (n=80) by immunohistochemistry, in relation to the clinical outcome of gastric cancer patients." (PMID 18087278, 2008). "In the current study, we investigated the population and localisation pattern of Foxp3+ T regs in gastric cancer by immunohistochemistry, and evaluated the relationship between the findings and clinical outcome." (PMID 18087278, 2008). "The present study is, to our knowledge, the first report describing the prevalence of Foxp3+ T regs related to the prognosis in gastric cancer." (PMID 18087278, 2008). "PD-1+ CD8+ T cells and FoxP3+ Tregs can serve as predictive biomarkers for immunotherapy resistance in gastric cancer, suggesting combination immunotherapy strategies could improve outcomes." (PMID 40723289, 2025). "According to literature, high density of tumor-infiltrating Tregs expressing Foxp3 correlated with poor outcome in breast, ovaries, lungs cancer, hepatocellular and renal cell cancer, pancreatic cancer, gastric cancer and cervix cancer." (PMID 40028198, 2025). "This indicates that in the gastric cancer microenvironment, Tregs-related molecules (FOXP3) and immune suppressive factors (IL10, TGF-β1), as well as checkpoint molecules (CTLA4), are highly expressed and enriched, jointly shaping an immunosuppressive microenvironment." (PMID 41438510, 2025). "This diverse immune infiltrate, including regulatory T cells (FOXP3+), mirrors the immunosuppressive microenvironment of human gastric cancer and may influence therapeutic responses to immunotherapy." (PMID 40673273, 2025). "Similarly, miR-133a-3p binds to FOXP3, suppressing its expression and stimulating autophagy in gastric cancer cells, thereby contributing to the stability of the tumor microenvironment." (PMID 41229433, 2025). "Compared to adjacent tissues, gastric cancer lesions contain significantly more FOXP3+ Tregs." (PMID 41229433, 2025). "However, high FOXP3 expression has been observed to correspond to higher survival in other cancers, such as gastric cancer, colorectal cancer, and non-small cell lung cancer." (PMID 39672307, 2024). "Under the regulation of Hp, gastric cancer stem cells can act as regulator of Th17/Treg ratio, Treg IL‐17− lymphocytes can be transferred to IL‐17+ phenotype while Th17 Foxp3− lymphocytes can become to Foxp3+ Tregs." (PMID 38349050, 2024).
gastric cancer (continued). "Also, the intratumoral CD4+FOXP3+ T-cells in gastric cancer (GC) engage with nearby immune effector cells, exerting their antitumor effects indirectly rather than through direct contact with tumor cells." (PMID 38339311, 2024). "In gastric cancer, FoxP3 could promote gastric cancer migration and invasion through the TGF-β pathway." (PMID 37569676, 2023). "We next detected CCL19 and FOXP3 in gastric cancer tissues by immunofluorescence staining." (PMID 37208608, 2023). "Treg cell expression was significantly upregulated in tumor samples compared with that in matched normal samples and patients with high FOXP3 expression had worse overall survival than those with low FOXP3 expression, suggesting that Tregs cells indicate poor prognosis in gastric cancer." (PMID 37208608, 2023). "In addition, FoxP3+ Tregs expressing CD39 were found to be better than FoxP3+ Tregs alone in predicting gastric cancer survival and time to recurrence of HCC." (PMID 36859386, 2023). "Analysis of 631 gastric cancer patients with 33 months of follow-up data in KMplotter database demonstrated that patients with high FOXP3 expression had worse overall survival (OS) than those with low FOXP3 expression, suggesting that Tregs cells indicate poor prognosis in gastric cancer." (PMID 37208608, 2023). "Evidence of an FOXP3 oncogenic behavior was also observed in gastric cancer." (PMID 36672296, 2023). "On the other hand, high levels of FoxP3-positive lymphocytes may signal better cancer prognoses, e.g., breast, prostate and gastric cancers." (PMID 36289746, 2022). "Thus, this study investigated the relationship between PSMD7 and FOXP3 and their roles in gastric cancer." (PMID 35037550, 2022). "MiR-133a could also regulate cell autophagy by binding to the 3′UTR of fork head Box P3 (FOXP3) in gastric cancer." (PMID 35012539, 2022). "However, several recent studies have shown that in addition to Tregs, FOXP3 has also been found to be expressed in various tumor cells, such as gastric cancer cells and renal cancer cells." (PMID 36550816, 2022). "PSMD7 and FOXP3 have the potential to be meaningful biological indicators of gastric cancer and may be applied to the development of novel agents or targeted therapy as candidate molecular targets." (PMID 35037550, 2022). "We hypothesized that the transcriptional activation of PSMD7 by FOXP3 may inhibit cell proliferation and facilitate cell apoptosis in gastric cancer." (PMID 35037550, 2022). "Similarly, both FoxM1 and FoxP3 were strongly expressed in gastric cancer, resulting in tumor metastasis, immune escape, and poor prognosis." (PMID 36301031, 2022). "ICOS+ Foxp3+ CD4+ T cells were abundantly observed in the late stages of gastric cancer." (PMID 35311157, 2022). "Some researchers have found that FOXP3 promotes metastasis in gastric cancer." (PMID 36235242, 2022). "CD8+ T and FOXP3+CD4+ T cells were important markers for diagnosis of gastric cancer." (PMID 33135337, 2020). "Foxp3+ tumor-infiltrating lymphocytes (TILs) appear to be crucially important in the process of gastric cancer development, and thus may serve as a prognostic marker associated with chronic H. pylori infection." (PMID 32206186, 2020). "In this study, we investigated PD-L1 expression in tumor and stromal immune cells, TILs (CD8+, FOXP3+, and PD-1+ cells), and their concomitant prognostic value in a large cohort of gastric carcinomas and in molecular groups stratified by EBV-infection and MSI status." (PMID 32498695, 2020). "Certain peripheral and tumor‐infiltrating immune cells, such as NK cells, CD3 + T cells, CD8 + T cells, and Foxp3 + Tregs, that are reportedly correlated with better gastric cancer prognoses, have been recommended for predicting prognosis and assessing therapeutic outcomes at the clinical level." (PMID 31631566, 2019).
gastric cancer (continued). "However, the tumor suppressor role of FOXP3 was disturbed under inflammatory microenvironment in gastric cancers, since FOXP3 interacts with two key transcription factors such as nuclear factor of activated T cells (NFAT) and NF-κB." (PMID 31815635, 2019). "FOXP3+ Tregs are abundant in gastric cancer tissues, and the high infiltration of FOXP3+ Tregs in tumors may indicate a better prognosis of gastric cancer." (PMID 30999966, 2019). "However, the number of Foxp3 cells was significantly (p < 0.01) higher in gastric cancer tissues (319 Foxp3+ cells per mm2) than in normal adjacent tissues (25 Foxp3+ cells per mm2)." (PMID 29025424, 2017). "These Bregs positively correlated with the levels of CD4+Foxp3+ Tregs in gastric cancer." (PMID 28470464, 2017). "However, after adding the ratio of CD8/Foxp3 for the further clustering analysis, more than 6–7 subtype gastric cancer immune phenotype formed, which indicated the complexity of classification." (PMID 29025424, 2017). "The group containing most of the gastric cancer tissues possessed higher PD-L1 and Foxp3 levels." (PMID 29025424, 2017). "All the samples clustered into 3 groups: one group contained two special samples of gastric cancer (higher CD8 expression), another contained most of the gastric cancer tissues (higher Foxp3 and PD-L1 expression), and the third group contained different types of gastric tissues." (PMID 29025424, 2017). "When we calculated the ratio of CD8+ and PD-L1+ cells, the ratios observed in normal adjacent tissues were also significantly higher than those in gastric cancer and normal gastric mucosa tissues, suggesting potential immunosuppressive roles for Foxp3 and PD-L1." (PMID 29025424, 2017). "Among all Tregs, Foxp3-expressing Tregs are well known to play a critical role in tumor immune evasion, which has been reported in a wide array of human malignancies including our study in gastric cancer." (PMID 29025424, 2017). "However, cell numbers of FOXP3-positive T cells were more decreased in gastric cancer cases showing weak NOVA1 expression in T cells." (PMID 26673617, 2016). "Regulatory T cells are potent immune suppressors and although their abundance in gastric tumors negatively correlates to patient survival, increased levels of the regulatory T-cell protein, FoxP3, a marker of regulatory T-cell activity, within gastric cancer cells coincides with a good prognosis." (PMID 28210674, 2015). "CCR7 positive score of gastric cancer cells and intratumoral FOXP3+ Treg cell number could be represented in the same scatterplot, from the scatterplot, two variables seemed to have a linear trend that could be carried out linear regression analysis." (PMID 24040244, 2013). "So far as we know, whether FOXP3+ Tregs are an unfavorable predictor for gastric cancer is still controversial." (PMID 24040244, 2013). "A subsequent in vitro study indicated that supernatants derived from gastric cancer cells under hypoxic condition, could induce the expression of Foxp3 via TGF-β1." (PMID 23723999, 2013). "Further studies will be needed to understand whether blockade of SLC/CCR7 interaction in combination with FOXP3+ Tregs depletion can inhibit the metastasis of gastric cancer cells to lymph nodes, and lead to better treatment outcomes or not." (PMID 24040244, 2013). "Multivariate analysis indicated that intratumoral FOXP3+ Tregs could be also an independent prognostic factor for patients with gastric cancer." (PMID 24040244, 2013). "Thus, Foxp3+ cells were analysed by immunohistochemistry in order to evaluate T regs in gastric cancer." (PMID 18087278, 2008). "Thus, PSMD7 silencing reversed FOXP3 overexpression-inhibited gastric cancer cell apoptosis." (PMID 35037550, 2022). "Overexpression of FOXP3 could rescue the effects of PSMD7 knockdown on gastric cancer cells." (PMID 35037550, 2022).